PRAG1 (PEAK1 related, kinase-activating pseudokinase 1)
Description:
Catalytically inactive protein kinase that acts as a scaffold protein. Functions as an effector of the small GTPase RND2, which stimulates RhoA activity and inhibits NGF-induced neurite outgrowth (By similarity). Promotes Src family kinase (SFK) signaling by regulating the subcellular localization of CSK, a negative regulator of these kinases, leading to the regulation of cell morphology and motility by a CSK-dependent mechanism (By similarity). Acts as a critical coactivator of Notch signaling (By similarity).
Synonyms: SgK223; DKFZp761P0423; PRAGMIN; PEAK2; NACK
Tractability: PROTAC: it is named in the literature on targeted protein degradation.
Gene: Protein-coding gene on chromosome 8 (8,317,736 to 8,387,357, reverse strand). Ensembl gene ENSG00000275342.
Subcellular location: Cytoplasm; Cell junction, focal adhesion; Nucleus
Subcellular location (Human Protein Atlas): Nucleoli; Focal adhesion sites
Pathways (Reactome):
Signal Transduction: RND2 GTPase cycle
Gene Ontology:
Molecular function: identical protein binding; protein binding; ATP binding; protein kinase activity
Biological process: cell migration; negative regulation of neuron projection development; positive regulation of Rho protein signal transduction; regulation of cell motility; regulation of cell shape; regulation of Notch signaling pathway
Cellular component: focal adhesion; cytoplasm; cytosol; nucleus
Genetic constraint (gnomAD): Loss-of-function variants: 87 observed, 80.29 expected, observed/expected ratio (o/e) 1.08, 90% interval 0.91 to 1.29. The synonymous counts are far from expectation, so gnomAD's model fits this gene poorly and the ratio says little. Missense variants: 2,215 observed, 1,629.9 expected, observed/expected ratio (o/e) 1.36, 90% interval 1.31 to 1.41. Synonymous variants: 895 observed, 705.74 expected, observed/expected ratio (o/e) 1.27, 90% interval 1.2 to 1.34.
Homologues: Orthologues: chimpanzee PRAG1 (99% identical), macaque PRAG1 (95% identical), guinea pig PRAG1 (79% identical), mouse Prag1 (76% identical), rat Prag1 (75% identical), tropical clawed frog prag1 (42% identical). Paralogues in human: PEAK1 (29% identical), PEAK3 (10% identical), PINK1 (9% identical).
Diseases named in the same sentence as PRAG1 in open-access papers:
PRAG1 is named in the same sentence as 23 diseases in open-access papers, as found by Europe PMC text mining. Sharing a sentence is not in itself a finding about the gene and the disease. The quoted sentences say what the papers report.
asthma (2 papers, 2021 to 2025). "PRAG1 has previously been linked to psychological outcomes, including selective serotonin reuptake inhibitors remission and neuroticism, however this is the first report to identify an association of PRAG1 with an asthma-related phenotype." (PMID 33477890, 2021).
Anxiety (1 paper, 2026). Intense feelings of nervousness, tension, or panic often arise in response to interpersonal stresses. "Knockout of Prag1 potentially leading to anxiety is supported by our results, as META-TWAS showed a negative effect size for PRAG1, meaning decreased levels of PRAG1 are associated with increased likelihood of anxiety." (PMID 41243181, 2026).
depression (1 paper, 2026). "Loci within PRAG1 influence selective serotonin reuptake inhibitors and neuroticism personality in patients with depression." (PMID 41243181, 2026).
endometriosis (1 paper, 2025). The growth of functional endometrial tissue in anatomic sites outside the uterine body. "Although the vagina is an uncommon site for endometriosis, genes such as CLDN23, MFHAS1, and PRAG1 showed notable functional associations." (PMID 40863222, 2025).
epilepsy (1 paper, 2025). A brain disorder characterized by episodes of abnormally increased neuronal discharge resulting in transient episodes of sensory or motor neurological dysfunction, or psychic dysfunction. "Additionally, some genes (TPRKB, PRAG1, SLC25A12, and TRIM8) have been identified as associated with epilepsy, a neurological disorder characterized by recurrent seizures, that shares similar genetic vulnerability with SZ." (PMID 40282399, 2025).
neuroblastoma (1 paper, 2025). Neuroblastoma (NB) is the most common solid, extracranial childhood tumor. "Given that previous studies have reported that PRAG1 forms punctate structures, we sought to further investigate whether PRAG1 forms dynamic condensates in cells by exogenously overexpressing PRAG1 in human neuroblastoma SH-SY5Y cells." (PMID 40149915, 2025).
Parkinson disease (1 paper, 2025). A progressive degenerative disorder of the central nervous system characterized by loss of dopamine producing neurons in the substantia nigra and the presence of Lewy bodies in the substantia nigra and locus coeruleus. "Remarkably, the formation of spherical PRAG1 condensates appears to be a common phenomenon in diverse stress models, as well as in dopaminergic (DA) neurons derived from a Parkinson’s disease patient." (PMID 40149915, 2025).
PRAG1 also shares sentences with these, for which no sentence is quoted: breast carcinoma (3 papers); cancer (3); pancreatic cancer (3); Epileptic encephalopathy (2); tumor (2); Colon Cancer (1); colorectal cancer (1); cystic teratomas of the ovary (1); gastric adenocarcinoma (1); gastric cancer (1); heart disease (1); ischemia reperfusion injury (1); neurodegenerative disease (1); neurological disorder (1); Obesity (1); type II diabetes (1).